ZNF704 (zinc finger protein 704)
Description:
Transcription factor which binds to RE2 sequence elements in the MYOD1 enhancer.
Synonyms: FLJ16218; Gig1
Tractability: PROTAC: ubiquitination databases record sites on it.
Gene: Protein-coding gene on chromosome 8 (80,628,451 to 80,874,781, reverse strand). Ensembl gene ENSG00000164684.
Subcellular location: Nucleus
Subcellular location (Human Protein Atlas): Nucleoplasm
Pathways (Reactome):
Gene expression (Transcription): Generic Transcription Pathway
Gene Ontology:
Molecular function: protein binding; sequence-specific double-stranded DNA binding; DNA-binding transcription factor activity; RNA polymerase II cis-regulatory region sequence-specific DNA binding; cis-regulatory region sequence-specific DNA binding
Biological process: regulation of transcription by RNA polymerase II
Cellular component: nucleus
Genetic constraint (gnomAD): Loss-of-function variants: 9 observed, 40.95 expected, observed/expected ratio (o/e) 0.22, 90% interval 0.13 to 0.38. The upper end of that interval is the gene's LOEUF score, 0.38, which puts it in group 1 of 6, group 1 being the genes least tolerant of losing a copy. Missense variants: 385 observed, 545.94 expected, observed/expected ratio (o/e) 0.71, 90% interval 0.65 to 0.77. Synonymous variants: 210 observed, 213.02 expected, observed/expected ratio (o/e) 0.99, 90% interval 0.88 to 1.11.
Homologues: Orthologues: chimpanzee ZNF704 (99% identical), macaque ZNF704 (99% identical), dog ZNF704 (96% identical), guinea pig ZNF704 (95% identical), pig ZNF704 (95% identical), mouse Zfp704 (89% identical), rabbit ZNF704 (83% identical), rat Zfp704 (78% identical), zebrafish znf704 (71% identical), tropical clawed frog znf704 (59% identical). Paralogues in human: ZNF395 (39% identical), SLC2A4RG (38% identical).
Diseases named in the same sentence as ZNF704 in open-access papers:
ZNF704 is named in the same sentence as 13 diseases in open-access papers, as found by Europe PMC text mining. Sharing a sentence is not in itself a finding about the gene and the disease. The quoted sentences say what the papers report.
breast carcinoma (6 papers, 2015 to 2025). "Less is known about ZNF704, though early research has linked it to uveal melanoma, chondrosarcoma, and breast cancer." (PMID 40050559, 2025). "Studies have reported that in breast cancer, the expression level of Znf704 is inversely associated with the expression level of Per2, and high levels of Znf704 are correlated with lymph node positivity, poor prognosis, and histological grading in patients with breast cancer." (PMID 38903177, 2024). "In conclusion, circHSDL2 regulates the Hippo pathway through the miR-7978/ZNF704 axis to facilitate the malignancy of breast cancer." (PMID 38937788, 2024). "Mechanistically, circHSDL2 acted as a sponge for miR-7978 to affect ZNF704 expression and thereby regulate the Hippo pathway in breast cancer cells." (PMID 38937788, 2024). "Prior studies suggested that up-regulation of ZNF704 gene was found to promote carcinogenesis in breast cancer." (PMID 37038184, 2023). "High ZNF704 expression is known to predict poor prognosis in lung cancer patients and ZNF704 amplification is observed in breast cancer; however, little is known about its role in other cancers." (PMID 37038184, 2023). "For example, the Zinc Finger Protein 704 (ZNF704)-SIN3 Transcription Regulator Family Member A (SIN3A) transcriptional repressor complex destabilizes period circadian regulator 2 (PER2) transcription, destabilizing circadian rhythms and driving breast cancer progression." (PMID 40725147, 2025).
uveal melanoma (3 papers, 2023 to 2025). A melanoma derived from melanocytes of the uveal tract. "For example, ZNF704 acts as an oncogene in BC, chondrosarcoma, and uveal melanoma by regulating circadian rhythm and AKT/mTOR signaling." (PMID 38429817, 2024).
osteoporosis (1 paper, 2022). A condition of reduced bone mass, with decreased cortical thickness and a decrease in the number and size of the trabeculae of cancellous bone (but normal chemical composition), resulting in increased fracture incidence. "Target genes with the highest number of miRNAs were DGKH, TNRC6B, ZNF704, INO80D and NFAT5, but according to the literature, none of these were ever directly associated with PTH or osteoporosis." (PMID 36011354, 2022).
tumor (6 papers, 2017 to 2025). "In addition, pan-cancer analysis revealed that ZNF704 was associated with tumor progression in several cancer types." (PMID 37038184, 2023). "Furthermore, ZNF704 operates through the AKT/mTOR/glycolysis signaling pathways, and the restoration of UM tumor cell viability in ZNF704-silenced cells can be achieved by knocking down SORBS3." (PMID 38920653, 2024). "Moreover, expression of SORBS3 is downregulated by ZNF704 and knockdown of SORBS3 restored tumor cell viability in ZNF704 silenced cells." (PMID 37038184, 2023). "Mechanistically, ZNF704 function as an oncogene by down-regulates SORBS3, which we demonstrated is a tumor suppressor in UM, and in turn activates PI3K/AKT/mTOR signaling pathway." (PMID 37038184, 2023). "Notably, genes such as NRG1, SAMD13, MFAP3L, SALL1, ZNF704, SEMA5A, and HLA-DQB1 were identified as having altered expression patterns, potentially reflecting the diverse roles of FGFRS in tumor biology." (PMID 39676867, 2024). "The worse prognosis remain true after adjusting for age, gender, or tumor stages, suggesting that ZNF704’s pro-oncogenic role was irrespective of other factors." (PMID 37038184, 2023).
cancer (5 papers, 2020 to 2025). A tumor composed of atypical neoplastic, often pleomorphic cells that invade other tissues. "The prognostic impact of ZNF704 expression in several types of cancer was investigated by pan-cancer analysis." (PMID 37038184, 2023). "Additionally, the gene targets of these miRNAs included several cancer driver genes including ZNF704 (targeted by ten miRNAs), MMP16 (targeted by eight miRNAs), and KCNN3, POU2F1, ADARB1, MPZL1, RUNX1T1, UBE2W, and DYRK1A genes (targeted by seven miRNAs)." (PMID 37685851, 2023). "Nevertheless, the role of ZNF704 in most cancers including UM is largely unknown." (PMID 37038184, 2023). "ZNF704 is a zinc finger protein and might be related with cancer." (PMID 32922442, 2020).
infection (1 paper, 2025). The state of being infected such as from the introduction of a foreign agent such as serum, vaccine, antigenic substance or organism. "In female samples, no gene was found to be regulated at all investigated time points, whereas one down-regulated gene (Zinc finger protein 704 (ZNF704)) and two up-regulated genes (EMILIN1, IL7R) were found over the total course of infection in male samples." (PMID 40794782, 2025).
ZNF704 also shares sentences with these, for which no sentence is quoted: chondrosarcoma (2 papers); amyotrophic lateral sclerosis (1); epilepsy (1); lung carcinoma (1); neurodegenerative disease (1); Obesity (1); skin cancer (1).